CD68 (CD68 molecule)
Diseases named in the same sentence as CD68 in open-access papers (continued):
Sharing a sentence is not in itself a finding about the gene and the disease.
tumor (continued). "In solid tumors, such as those of the breast and pancreas, infiltrating Cluster of differentiation 68 (CD68)+ or Cluster of differentiation 163 (CD163)+ tumor-associated macrophages are correlated with poor outcomes and immunosuppression." (PMID 39055564, 2024). "In ccRCC samples with upregulated CCL5, there is a significant increase in the proportion of CCL5 + tumor-associated macrophages (TAMs) and PD-L1 + CD68 + TAMs, indicative of a typical immunosuppressive tumor immune microenvironment." (PMID 39014460, 2024). "At the invasion front of SARIFA-positive PDAC, we observed significantly higher expression of FABP4 (p < 0.0001) and higher concentrations of CD68+ macrophages (p = 0.031) related to a higher risk of tumour progression." (PMID 38926671, 2024). "This is in line with a previous study where VISTA expression has been correlated with amplified CD68+ tumor-associated macrophages in pancreatic tumors resulting in poor clinical outcomes." (PMID 38553748, 2024). "A tissue microarray (TMA) of CRC patients offering paired tumor and tumor‐adjacent mucosa was used to analyze an association of Rep (and CD68) expression with clinic‐epidemiological parameters including patient survival." (PMID 36811271, 2024). "CD68(+) (pan-TAM marker) TAM is significantly increased in tumor tissues and significantly associated with poor patient prognosis." (PMID 39678502, 2024). "In OSCC, PLIN3High tumors harbored obviously less infiltrated CD8+ T lymphocytes and CD4+ T lymphocytes, whereas CD56+ NK cells, CD68+ tumor-associated macrophages (TAMs), and CD19+ B lymphocytes were essentially comparable." (PMID 38554152, 2024). "Conversely, higher counts of FOXP3+ regulatory T‐cells and CD68+ macrophages have been linked to an immune‐exclusion phenotype and tumor recurrence." (PMID 38017652, 2024). "In one of the patients from each of the lead-in groups (A-2 and S-2), increases in CD19+ tumor-infiltrating B cells, CD68+ tumor-associated macrophages, CD4+ and CD8+ T cells (CD3+), as well as FOXP3+ regulatory T cells, were also observed." (PMID 38672538, 2024). "Conversely, the density of CD68+ tumor associated macrophages (TAMs) and PD1−FoxP3+CD4+ regulatory T (TREG) cells was comparable in the mTLSs of HGSOC and NSCLC samples." (PMID 38514660, 2024). "SPP1-expressing TAM subpopulations have been shown to promote intravasation and metastasis in HNSCC and low TAM containing tumours (CD68 CD163) have been associated with better survival." (PMID 38803348, 2024). "Although the total CD68+ TAMs infiltration in the tumor was significantly associated with poor OS, the survival outcomes of CD68+ TAMs in TI and TS were inconsistent." (PMID 38501293, 2024). "To delineate the immune context of LLT1TC high patients, we evaluated the distribution of CD4+ T cells, CD8+ T cells, Foxp3+ Tregs, CD68+ tumor‐associated macrophages, and CD19+ B cells." (PMID 38502058, 2024). "A high ratio of CD163/CD68 in tumor stage MF and SS suggests M2 polarization of TAMs, which is associated with tumor advancement." (PMID 39703508, 2024). "High expression of CD20 and CD68 in the pre-treatment tumour samples was positively associated with the pathological response." (PMID 39164491, 2024). "This was also corroborated by IMC results where tumors presented lower frequencies of cells expressing macrophage markers like CD68, F4/80 as well as suppressive tumor associated macrophage markers like CD163 and CD206." (PMID 38206570, 2024). "We considered the whole TCGA BLCA dataset that includes both clinical and RNA-seq data of 404 patients, to correlate the expression of the transcript encoding the CD44v6 isoform and the CD68+ cell fraction in tumor samples with clinical features of patients." (PMID 38600583, 2024). "CD68 expression in the peritumor showed an association with a less favorable prognosis while tumor CD68 expression was linked with a beneficial prognosis, which was reported in serval studies." (PMID 36811271, 2024).
tumor (continued). "To do so, we first performed IHC staining to observe the presence of tumor-associated macrophages (TAMs) including CD68+ M1 and CD206+ M2 macrophages in the lung metastatic loci." (PMID 38037106, 2023). "CD‐68 positive macrophage infiltration has been associated with poor prognostic BC features such as higher tumour grade, larger tumour size, lymph node metastasis, hormone receptor negativity, HER‐2 expression and an increase of Ki‐67 level." (PMID 37553911, 2023). "Lastly, EV-S100A9 levels in plasma and tissue CD68 macrophage infiltration at rHGP metastatic tumour boundaries are strongly associated with each other and with poor patient survival." (PMID 39516397, 2023). "An increased expression of CD68 stained tumor-associated macrophages has demonstrated a positive correlation to angiogenesis, consistent with hypoxia." (PMID 37488490, 2023). "The IL-22 expression in tumors was a poor prognostic factor for OS, and along with tumor-IL-22R1, was positively associated with the infiltration of CD68-positive TAM, which together displayed the worst prognosis outcomes regarding both OS and RFS." (PMID 37835465, 2023). "The authors showed that PD-L1+ FOXP3+ CD4+ (T-regulatory) cells coexisted with CD68+ and PD- L1+ CD68+ tumour-associated macrophages (TAMs) in the stroma of ARID1Amut low-risk patients." (PMID 37569458, 2023). "For example, SERPINA1 showed close connections to CD8A in CD8+ T cells, CD68 in tumor-associated macrophages, IRF6 in M1 macrophages, NRP1 in DCs, STAT3 and IL17A in Th17 in most digestive cancers." (PMID 37511325, 2023). "While Il4r and Igf1 mRNA was expressed in Cd68/Aif1-positive tumour-associated microglia throughout drug-treated PDOX, Il4 expression co-localised with Gfap/S100b-expressing astrocytes exclusive to the interface region of drug-treated PDOX." (PMID 37127652, 2023). "On the other hand, we observed that higher densities of CD68+MRP8-14+CD86neg M1 macrophages in the tumor center is associated with poor overall survival compared with the low densities in CLM." (PMID 37637998, 2023). "Serum IL-34 and MCSF, or intrahepatic IL-34, MCSF and CD68+ tumor associate macrophages (TAMs) were determined using ELISA or immunohistochemistry." (PMID 35347503, 2023). "It has been shown that increased density of CD68+ tumor-associated macrophages (TAMs) is associated with increased vascular and lymphatic invasion in HNSCC, and Vimentin is known to be associated with tumor growth and metastasis in cancer." (PMID 37387167, 2023). "Based on the importance of TAM in cancer progression, in our IHC validation analysis, high CD44 expression of tumor cells was associated with high levels of CD68 + macrophages." (PMID 37316699, 2023). "The association between CD68+ macrophages and patient survival is somewhat ambiguous, although the location of CD68+ macrophages at the tumor border is indicative of worse patient outcomes." (PMID 37762707, 2023). "The literature extensively reports that overexpression of CD68+ cells in the tumor microenvironment is associated with decreased progression-free survival (PFS), overall survival (OS), and increased risk of relapse." (PMID 38024830, 2023). "C3aR was observed in tumor-associated macrophages (TAM) expressing CD68, CD18, CD163, and the proangiogenic VEGF." (PMID 37174113, 2023). "A good response to NET defined as a decrease in tumour size and/or decrease of Ki‐67 was found to be associated with a longer duration of NET, a change of CD4+ T‐cells, and a higher number of CD68+ tumour‐associated macrophages before the start of NET." (PMID 37553911, 2023). "MIF staining revealed that TRG 1–3 group was associated with a higher density of PD‐L1+/CD68+ cells in the pre‐treatment tumor parenchyma than TRG 4–5 group (p = 0.048)." (PMID 36341590, 2023). "VISTA expression was highest in CD68+ tumor-associated macrophages compared to other immune cell types in breast cancers but most prominent in the basal-like genotype." (PMID 36891296, 2023).
tumor (continued). "Tumor-associated macrophages (CD68, CD163), cytotoxic T cells (CD8), and regulatory T cells (FoxP3) were quantified via three methods." (PMID 37543970, 2023). "IHC staining results further confirmed that the expression of CD44 in tumor cells was positively associated with the number of CD68+ macrophages and CD163+ macrophages (P < 0.05)." (PMID 37316699, 2023). "We found that BEST1 was mainly expressed on monocytes (CD14+) and tumor‐associated macrophages (TAMs) (CD68+) in the TME of HNSCC patients, and the positive ratio of BEST1 expression in cancer is significantly elevated than that in adjacent normal tissue." (PMID 37088729, 2023). "Previous studies had reported that RRX-001 exhibits potent anti-cancer activity on tumors dependent on the presence of tumor-associated macrophages in tumor tissue, so we assessed the macrophages indicated by CD68 in GCTs treated before and after RRX-001." (PMID 36823373, 2023). "The increased presence of FOXP3 Tregs and CD68 macrophages have been linked to poor survival and tumor growth in NPC via NF-κB pathway alterations." (PMID 37046826, 2023). "Clusters of CD68+ cells were observed at the periphery of the tumoroids, likely representing tumor-associated macrophages (TAMs) that are the most abundant immune cell population infiltrating the tumor microenvironment." (PMID 37736770, 2023). "We evaluated IL-10-producing CD68+ tumor-associated macrophages (TAMs) in cancer tissue from GC patients." (PMID 37153541, 2023). "This supports the assumption that themajority of tumor-associated macrophages with CD68 positivity are of an M2phenotype also expressing CD163." (PMID 36880147, 2023). "Tumor-associated macrophages (TAMs) were identified by CD68, CD14, CD163 and HLA-DRA and cancer-associated fibroblasts (CAFs) were characterized by COL1A1, COL3A1, MMP2, and SPARC." (PMID 37007745, 2023). "CD68 was a marker of tumor‐associated macrophages, and was associated with both favorable and unfavorable outcomes." (PMID 38133211, 2023). "Some studies have suggested that a significant fraction of CD45+ CK+ cells also express CD68, which is a marker associated with tumor-associated macrophages." (PMID 36768881, 2023). "High CD73 expression was associated with a higher ratio of Foxp3 + /CD8 + tumor-infiltrating lymphocytes (TILs) and CD163 + /CD68 + tumor-associated macrophages (TAMs)." (PMID 36899373, 2023). "In the case of the CD68 gene, high levels of CD68 are associated with higher tumor grade, larger tumor size, Ki67 positivity, and other malignant features, indicating tumor progression and aggressiveness." (PMID 37693315, 2023). "For instance, in a 30-patient Japanese CRC cohort, a lower density of CD68+ in the tumor stroma and invasive front were linked to more progressive cancer, whereas high levels of TAMs were linked to a favorable prognosis." (PMID 37525217, 2023). "P2Y12 expression was confirmed on CD68+ CD163+ tumor-associated macrophages of melanoma in situ where P2Y12 triggers the migration of macrophages towards nucleotide-rich, necrotic tumor areas, and modulates the inflammatory environment upon ADP binding." (PMID 37047682, 2023). "A CD68 (a marker for tumor-associated macrophages) staining showed that the COX-2-positive staining was not due to infiltration of COX-2-expressing macrophages in inflammatory responses to cancer cell inoculation and tumor growth." (PMID 38139248, 2023). "We confirmed Cd68/Aif1-expressing tumour-associated microglia and Gfap/S100b-expressing astrocytes in close proximity to proliferating (MKI67-positive) tumour cells within the interface of drug-treated PDOX." (PMID 37127652, 2023). "In the multivariate analysis, the BCLC C stage; the MVI status; the density of TILs; and the expressions of CD66b, OX40, and PD-L1 in tumor-infiltrating immune cells, CD68, and CD8, were significantly associated with OS." (PMID 35936682, 2022).
tumor (continued). "We compared proportions of CD3+, CD4+, and CD8+ T cells, CD57+ natural killer (NK) cells, CD4+ FOXP3+ regulatory T cells (Tregs), and CD68+ CD163+ M2 tumor-associated macrophages (TAMs) between paired ACC and SCCC samples, respectively." (PMID 36032124, 2022). "We found that high infiltration of CD8-positive T cells in tumor tissue, high expression of CD68-positive tumor-associated macrophages, and low expression of CD4-positive T cells was significantly associated with good response to ICI treatment and survival." (PMID 36437290, 2022). "CD68 serves as a pan-macrophage marker for tumor-associated macrophages, and CD163-labeled macrophages are mainly M2 macrophages, which promote tumor growth and metastasis." (PMID 36195882, 2022). "Immune infiltration analysis shows that NRAS is positively correlated with the levels of CD68+ tumor-associated macrophages in HCC samples and that NRAS and CD68 are related to the poor outcome of HCC." (PMID 36348379, 2022). "Our analysis indicates that a high CD68+ TAM density in the tumor stoma was significantly linked with poor OS (HR 2.46, 95% CI, 1.83-3.31, P<0.001) and shorter DFS (HR 1.77, 95% CI, 1.08-2.89, P=0.02) compared to low CD68+ TAM density." (PMID 35847911, 2022). "Immunostaining of tumor excised from mice treated with CC exhibited significant decrease in proliferation index (nuclear ki67), mean vascular density (CD31), and tumor associated macrophages infiltration (CD68) immunostaining." (PMID 36291886, 2022). "Our results revealed a strong association between HMGA2 expression in tumor cells and CD68 expression in the stroma." (PMID 34976223, 2022). "CD68 is a pan-macrophage marker that has been extensively used to identify both M1 and M2 tumor-associated macrophages (TAMs) when combined with other macrophage markers." (PMID 36520870, 2022). "CD8 is a marker of killer T lymphocytes and CD68 is a marker of tumour-associated macrophages (TAM)." (PMID 35675033, 2022). "In this panel, CD68 was chosen as a pan-macrophage marker corresponding with tumor-associated macrophages (TAMs)." (PMID 36050391, 2022). "We subsequently evaluated the landscape of FOXP3+ Tregs and CD68+ tumor-associated macrophages (TAMs) in HR/MMR-intact versus HR-d tumors." (PMID 35547873, 2022). "Meanwhile, Tumor associated macrophages shifted towards anti-tumor M1-like subtypes, with CD68+CD163+ M2-like subpopulation significantly decreased (P = 0.04)." (PMID 36686751, 2022). "Increasing evidence has shown that CD68 is a promising tumor-associated diagnostic and prognostic marker for cancer." (PMID 35550532, 2022). "ARID1A mutant cases showed significantly higher CD8+ cells and CD68+ cells (tumour‐associated macrophages, TAMs) in the stroma relative to tumour." (PMID 35647895, 2022). "We used the CD68 marker to stain the amount of tumor-associated macrophages and the IL-1β as a signal for the NLRP3 inflammasone activation." (PMID 35884397, 2022). "Infiltration levels of SPP1+CD68+ tumor-associated macrophages (TAMs) were examined by dual immunofluorescence (IF) staining in 264 resected ICC samples." (PMID 35558087, 2022). "The presence of CD68+ macrophage infiltrates in the primary tumor tissue was also significantly associated with an intraindividual increase in the MIB-1 index." (PMID 35453901, 2022). "In parallel, approximately 32% of the tumor-associated macrophages (CD68+) showed an M2-polarized subtype (CD163+)." (PMID 36010653, 2022). "We recently reported that statin use is associated with a reduction in CD68+CD163+ pro-tumourigenic tumour-associated macrophage (TAM) proportions in tumour parenchymal and stromal areas of human lung adenocarcinomas." (PMID 34779486, 2022). "CD68+ tumor-associated macrophages (TAMs), instead of T cells and B cells, were found to be the main resource of PLIN2 in OSCC stroma and lung, pancreas, prostate, and testis." (PMID 35372038, 2022).
tumor (continued). "Despite their distribution variations among different TET categories, both TAM populations (CD68+ and CD 163+) are associated with tumor invasion and nodular metastases." (PMID 35887212, 2022). "We demonstrate by staining serial sections that IL18 was mainly expressed by M1-like (CD68+/CD163-) tumor-associated macrophages (TAM) but also M2-like (CD68+/CD163+) TAMs in our cohort." (PMID 36131941, 2022). "The quantification of mesenchymal cells (ACTA2+), and tumor associated microglia/macrophages (TAM) cells (CD68+ and IBA1+) showed a significant enrichment of these populations within oncostreams compared to the surrounding areas." (PMID 35750880, 2022). "We conducted immunostaining of the tumor-associated macrophage biomarkers CD68/CD163 and double staining for PAS/CD31 in ccRCC human specimens to find that higher TAM infiltration was positively correlated with VM formation." (PMID 35443741, 2022). "For this reason, CD68 alone or in combination with other cell markers of tumor-associated macrophages (TAMs) is a good predictive value of survival in cancer patients." (PMID 35884397, 2022). "Kaplan–Meir survival analysis of disease-specific survival (considering all cases) showed a direct association of high SIRPα/CD68-ratio in inner tumor areas with poor prognosis (p = 0.02)." (PMID 35406573, 2022). "Levels of CA12+CD68+ cell infiltration were positively associated with the metastatic potential of tumor patients (P = 0.032)." (PMID 35362480, 2022). "Tumor stroma rich in ERα36high CAFs was correlated with high Ki67 expression (p = 0.041) and tumor-associated macrophages markers (CD68 and CD163, p = 0.041 for both)." (PMID 35454913, 2022). "Tumor-associated macrophage staining (CD68) of tumor biopsies of nine patients obtained at baseline before local ablation revealed tumor regions with CD163+ cells in all patients." (PMID 36353535, 2022). "The synchronous GGNs had significantly fewer CD8+ T cells and more CD68+ tumor-associated macrophages compared with primary lesions." (PMID 35008406, 2022). "DRS measurements were correlated to end-point immunohistochemistry (IHC) markers of hypoxia (carbonic anhydrase-9) and microvasculature (CD31), along with tumor-associated macrophage recruitment (CD68) and M2 tumor-associated macrophage recruitment (CD163)." (PMID 35461243, 2022). "Our results from human CRC specimens also revealed a strong positive association between HMGA2 expression in tumor cells and CD68 expression in the stroma." (PMID 34976223, 2022). "More importantly, high expression of circSMARCC1 was positively associated with colonization of CD68+/CD163+/CD206+ TAMs in tumor microenvironment." (PMID 36045408, 2022). "Further, we demonstrated that ameboid TAMs and increased cell proliferation within the tumor are associated with CD68 expression." (PMID 36589283, 2022). "CD68, alone or in combination with other tumor-associated macrophage markers, had a high predictive value for survival in cancer patients." (PMID 36276869, 2022). "Despite the significant association between the SIRPα/CD68-ratio in the invading front and inner tumor areas (p < 0.0001, r = 0.75), the ratio differed in 30/98 cases." (PMID 35406573, 2022). "Among CD8+ T cells, M1 (CD68+HLA-DR+) tumor-associated macrophages (TAMs), M2 TAMs (CD68+HLA-DR-), CD56bright NK cells and CD56dim NK cells, less CD8+ T cell infiltration was found in the EGFR mutation group than in the group without EGFR mutation (p<0.05)." (PMID 35265073, 2022). "Male sex, low plasma fibrinogen levels and diffuse CD68+ macrophage infiltrates were found to be significantly associated with an increase in the MIB-1 labeling index in recurrent tumor tissue samples." (PMID 35453901, 2022). "A direct association was also noted with the SIRPα/CD68-ratio (p = 0.04, r = 0.21 for the invading front; p = 0.03, r = 0.21 for inner tumor areas)." (PMID 35406573, 2022).